CCNG1 (cyclin G1)
Description:
May play a role in growth regulation. Is associated with G2/M phase arrest in response to DNA damage.
Synonyms: CCNG
Tractability: PROTAC: ubiquitination databases record sites on it.
Gene: Protein-coding gene on chromosome 5 (163,437,569 to 163,448,199, forward strand). Ensembl gene ENSG00000113328.
Subcellular location: Nucleus
Subcellular location (Human Protein Atlas): Nucleoplasm
Gene Ontology:
Molecular function: protein binding; cyclin-dependent protein serine/threonine kinase regulator activity
Biological process: regulation of cyclin-dependent protein serine/threonine kinase activity
Cellular component: nucleoplasm; cyclin-dependent protein kinase holoenzyme complex; nucleus
Genetic constraint (gnomAD): Loss-of-function variants: 8 observed, 22.29 expected, observed/expected ratio (o/e) 0.36, 90% interval 0.21 to 0.65. The upper end of that interval is the gene's LOEUF score, 0.65, which puts it in group 2 of 6, group 1 being the genes least tolerant of losing a copy. Missense variants: 228 observed, 279.34 expected, observed/expected ratio (o/e) 0.82, 90% interval 0.73 to 0.91. Synonymous variants: 95 observed, 105.01 expected, observed/expected ratio (o/e) 0.9, 90% interval 0.76 to 1.07.
Homologues: Orthologues: chimpanzee CCNG1 (100% identical), macaque CCNG1 (99% identical), dog CCNG1 (98% identical), pig CCNG1 (97% identical), guinea pig CCNG1 (96% identical), rat Ccng1 (93% identical), mouse Ccng1 (92% identical), tropical clawed frog ccng1 (76% identical), zebrafish ccng1 (63% identical), Caenorhabditis elegans cye-1 (18% identical), Drosophila melanogaster CycE (18% identical), Drosophila melanogaster CycA (17% identical), and 9 more. Paralogues in human: CCNG2 (52% identical), CCNI (27% identical), CCNI2 (21% identical), CCNA2 (21% identical), CCNA1 (20% identical), CCND3 (20% identical), CCNJL (20% identical), CCNJ (19% identical), CCND2 (19% identical), CCNO (17% identical), CCNB2 (17% identical), CCNF (16% identical), and 6 more.
Diseases named in the same sentence as CCNG1 in open-access papers:
CCNG1 is named in the same sentence as 73 diseases in open-access papers, as found by Europe PMC text mining. Sharing a sentence is not in itself a finding about the gene and the disease. The quoted sentences say what the papers report.
hepatocellular carcinoma (21 papers, 2010 to 2024). A malignant tumor that arises from hepatocytes. "Huh7 is a hepatoma cell that exhibits constitutive expression of miR-122 which is associated with low Cyclin G1 expression level in hepatic cells." (PMID 24813441, 2014). "MSC EVs overexpressing miR-122 were used to downregulate domain-containing protein 10 (ADAM10), insulin-like growth factor 1 receptor (IGF1R), and cyclin G1 (CCNG1), three proteins implicated in hepatocellular carcinoma." (PMID 34830787, 2021). "miR-122 was found to sensitize hepatocellular carcinoma (HCC) cells to ADR and VCR by inducing cell cycle arrest, and this effect was associated with CCNG1." (PMID 26623719, 2016). "Enhanced expression of cyclin G1 (CCNG1) contributed to drug resistance of hepatoma cells and increased recurrence rate in HCC patients." (PMID 26514126, 2015). "For instance, miR-15b induced cell cycle arrest at G0/G1 phase by targeting cyclin E in glioma cells; miR-16 induced G1 arrest partially by targeting cyclin D1; miR-122a can modulate cyclin G1 expression in human hepatocellular carcinoma-derived cell lines." (PMID 24984770, 2014). "An inverse correlation between miR-122 and CCNG1 exists in primary liver carcinoma, further emphasizing the importance of miR-122 in HCC pathogenesis." (PMID 21286309, 2010). "In previous reports, it has been shown that miR-122a plays a role in the genesis of hepatocellular carcinoma by blocking cyclin G1 expression." (PMID 21192833, 2010). "Some have suggested that CCNG1 might function as an oncogenic protein and play a pivotal role in the initiation and metastasis of hepatocellular carcinoma." (PMID 26872615, 2016). "The suppression of miR-122 by HOTAIR through DNA methylation resulted in the activation of Cyclin G1 and enhanced tumor growth in hepatocellular carcinoma (HCC)." (PMID 38132140, 2023). "A previous study showed that miR-122 acts as a tumour suppressor by regulating oncogenes such as cyclin G1, AKT3, and CDK4 in hepatocellular carcinoma." (PMID 38820252, 2024). "Studies have demonstrated Ccng1’s ability to promote apoptosis in MPC5 cells and induce selective autophagic degradation in hepatocellular carcinoma by impeding G cell cycle progression and inhibiting DNA synthesis." (PMID 38728287, 2024). "The known mRNA interactors of miR-122 include PKM2, AKT1, MYC, TGFBR1, and SMAD4 in hepatocellular carcinoma, JNK, AP1, and caspases 3/8 in irritable bowel disease, and AKT, PI3K, PCNA, MTDH, PI3K, TRIM29, Bcl-W, CCNG1, and ALDO2 in CRC." (PMID 36499586, 2022). "It was further demonstrated that miR-122 inhibits hepatocellular carcinoma metastasis by modulating ADAM17 (a disintegrin and metalloprotease 17) and cyclin G1 (CCNG1)." (PMID 34072348, 2021). "Other studies have revealed that miR-122 is a tumor suppressor through modulating oncogenes including CDK4, cyclin G1, and AKT3 in hepatocellular carcinoma (HCC)." (PMID 35651814, 2022).
breast carcinoma (13 papers, 2008 to 2025). "According to these researchers, the cyclin G1 knockdown in MCF7 significantly limits cell viability and clonogenic ability, indicating that estradiol is related to breast cancer cell proliferation via increasing cyclin G1 expression." (PMID 33406787, 2021). "One novel aspect of this study is that cyclin G1 was found to be a critical target gene that mediated estradiol- and progesterone-induced breast cancer cell proliferation." (PMID 29513878, 2018). "Our data indicated that novel therapeutics against cyclin G1 are promising for the treatment of estrogen- and progesterone-mediated breast cancer progression." (PMID 29513878, 2018). "The increased proliferation of breast cancer cells was achieved by inducing the expression of cyclin G1." (PMID 29513878, 2018). "In contrast, our data suggest that targets against cyclin G1 are promising therapeutics for the treatment of breast cancer." (PMID 29513878, 2018). "Increased levels of CCNG1 were found in several human tumours such as breast cancer and osteosarcoma." (PMID 27528885, 2016). "Altered regulation of CCNG1 has been observed in breast cancer." (PMID 18535662, 2008). "Therefore, therapeutics against cyclin G1 might prove to be promising for the treatment of breast cancer." (PMID 29513878, 2018).
lung carcinoma (9 papers, 2016 to 2024). "On the contrary, high levels of CCNG1 were correlated with an increased overall survival of these patients, pointing the high expression of CCNG1 as a good prognostic factor in lung cancer." (PMID 28860486, 2017). "CCNG1 was reported to function as a suppressor of tumor proliferation in breast and lung cancer." (PMID 26623719, 2016). "Furthermore, miR-23b-3p could also inhibit cell proliferation in lung carcinoma by regulating the expression of cyclin G1 (CCNG1), which has been reported as an oncogene in OS development." (PMID 31779647, 2019). "In addition, overexpression of CCNG1 (cyclin G1) and MEF2D (myocyte enhancer factor 2D), two targets of miR-122 also abolished the antitumor effect in lung cancer, which indicates that oleanolic acid may inhibit lung cancer growth through miR-122/CCNG1/MEF2D pathway." (PMID 28052018, 2017).
ovarian carcinoma (8 papers, 2016 to 2024). A malignant neoplasm originating from the surface ovarian epithelium. "Similar results were seen in A2780 cells (3.234 ± 0.445 μg/mL vs 5.084 ± 0.214 μg/mL, P: 0.003), suggesting that CCNG1 overexpression was associated with ovarian cancer chemotherapy resistance." (PMID 30565428, 2019). "Additionally, as evidenced by our data, CCNG1 overexpression reduced the sensitivity of ovarian cancer cells to cisplatin and was associated with a shorter survival, and vice versa." (PMID 30565428, 2019). "We quantified MIR23B and CCNG1 mRNA expression in normal ovary tissue, benign and borderline tumors, and primary ovarian carcinoma using real-time PCR." (PMID 26872615, 2016). "CCNG1 mRNA expression was significantly lower in normal ovarian tissues than in benign tumors, borderline tumors, and ovarian carcinomas, and expression among pathological subtypes was significantly different." (PMID 26872615, 2016). "CCNG1 mRNA expression was significantly lower in the normal ovarian tissues and benign ovarian tumors than in the ovarian carcinomas (p < 0.05)." (PMID 26872615, 2016). "We found that CCNG1 mRNA expression was significantly lower in the normal ovarian tissues and benign ovarian tumors than in the borderline ovarian tumors and ovarian carcinomas." (PMID 26872615, 2016). "Similarly, elevated miR-1271 worked as an inhibitor in ovarian cancer due to its inhibitory role in cell proliferation and tumor growth by directly targeting cyclin G1." (PMID 32448371, 2020). "Down‐regulation of NICD3 by shRNA resulted in decreased CCNG1 expression, suggesting that NICD3 may be the upstream regulator of CCNG1 in ovarian cancer cells." (PMID 30565428, 2019). "MiR23b was shown to target cyclin G1 and suppress ovarian cancer tumorigenesis and progression." (PMID 29499737, 2018). "MiR-23b also can target cyclin G1 to suppress ovarian cancer progression." (PMID 28449663, 2017). "Our findings show that miR-23b may inhibit ovarian cancer tumorigenesis and progression by downregulating CCNG1 and the expression of the relevant genes." (PMID 26872615, 2016). "Our findings show that miR-23b may inhibit ovarian cancer tumorigenesis and progression by downregulating CCNG1 and the expression of the relevant genes, and that miR-23b is a potentially novel application for regulating ovarian carcinoma progression." (PMID 26872615, 2016). "We suggest that miR-23b may also be a potential suppressor of ovarian carcinoma by targeting CCNG1." (PMID 26872615, 2016). "CCNG1 (cyclin G1) plays a crucial role in ovarian cancer progression, and miR-1271-5p targets the 3′UTR of CCNG1, leading to its inhibition." (PMID 38793064, 2024). "In vitro and in vivo experiments demonstrated that CCNG1 promoted EMT and facilitated metastasis of ovarian cancer cells." (PMID 30565428, 2019).
osteosarcoma (7 papers, 2016 to 2026). A usually aggressive malignant bone-forming mesenchymal neoplasm, predominantly affecting adolescents and young adults. "Studies have confirmed that CCNG1 is overexpressed in osteosarcoma tissues, and the inhibition or knockout of CCNG1 can inhibit cell proliferation and colony formation, indicating that CCNG1 negatively regulates cell growth." (PMID 36588792, 2022). "Furthermore, luciferase reporter assays confirmed that CCNG1 is a direct target of miR‐27a in human osteosarcoma cells." (PMID 32133790, 2020).
gastric cancer (5 papers, 2016 to 2022). A primary or metastatic malignant neoplasm involving the stomach. "For example, miR-27b could enhance the sensitivity of gastric cancer cells to several chemotherapeutic drugs by suppressing CCNG1, suggesting that CCNG1 may contribute to chemoresistance." (PMID 33245102, 2020).
pancreatic cancer (4 papers, 2010 to 2022). "Though, it has been reported that LINC01133 has a carcinogenic role as it activates CCNG1 in pancreatic cancer." (PMID 36371178, 2022). "Recent studies have reported that CCNG1 gene therapy has been developed and has undergone phase I/II clinical trials for treating colorectal and pancreatic cancer." (PMID 26872615, 2016). "Overexpression of AP-2α in pancreatic cancer cells was shown to reduce tumor growth through an altered expression pattern of cell cycle-controlling factors such as CDK-4, CDK-6, Cyclin-G1, p27kip1 and p57kip2." (PMID 20805990, 2010). "Recently, overexpression of AP-2α in pancreatic cancer cells was shown to reduce tumor growth through an altered expression pattern of cell cycle-controlling factors such as CDK-4, CDK-6, cyclin-G1, p27kip1 and p57kip2." (PMID 20805990, 2010).
liver cancer (3 papers, 2014 to 2016). An epithelial or non-epithelial malignant neoplasm that arises from the liver. "It has been shown that loss of Cyclin G1 inhibited both the initiation stage and progression of liver cancer induced by DENA." (PMID 25431954, 2014). "Several studies showed that CCNG1 plays important roles in liver cancer." (PMID 26623719, 2016).
myeloid tumors (3 papers, 2022 to 2023). "Focused studies of IGH rearrangements in myeloid neoplasms identified an IGH-CCNG1 breakpoint translocation at the cyclin G1 (CCNG1) promoter, which demonstrated overexpression of CCNG1 in the patient’s bone marrow." (PMID 39086682, 2023).
pancreatic ductal adenocarcinoma (3 papers, 2020 to 2022). An infiltrating adenocarcinoma that arises from the epithelial cells of the pancreas. "It was reported that linc01133 could promotes cell proliferation in pancreatic ductal adenocarcinoma through upregulation of cyclin G1." (PMID 35017464, 2022).
viral infection (3 papers, 2021 to 2023).
endometrial carcinoma (2 papers, 2018). A malignant tumor arising from the epithelium that lines the cavity of the uterine body. "A deficiency in progesterone and its receptors is an important cause of decreased expression of cyclin G1 in endometrial carcinoma." (PMID 29513878, 2018). "In contrast, in hepatic tumors and cervical carcinoma, overexpression of cyclin G1 has been shown to promote cell growth, which contradicts the results for endometrial carcinoma." (PMID 29513878, 2018). "CCNG1 (Cyclin G1) showed an up-regulation significant in the endometrial cancer patient group at the early time-points of 24 hr and 48 hr while in the head and neck cancer patients we detected up-regulations that were not statistically significant." (PMID 29474504, 2018). "For example, cyclin G1 is known to exert negative control of cell proliferation in endometrial carcinoma in a progesterone-dependent manner." (PMID 29513878, 2018).
glioma (2 papers, 2014 to 2020). A benign or malignant brain and spinal cord tumor that arises from glial cells (astrocytes, oligodendrocytes, ependymal cells). "lncRNA 01494 enhanced cell proliferation, migration, and invasion via regulation of miR-122-5p/CCNG1 axis in glioma." (PMID 32322669, 2020).
head and neck cancer (2 papers, 2016 to 2018). A primary or metastatic malignant neoplasm affecting the head and neck. "Overall, an up-regulation of PHPT1, CCNG1, CDKN1A, GADD45, and SESN1 was found in endometrial and head and neck cancer patients at all time points with the exception of SESN1." (PMID 29474504, 2018). "Because both CCNG1 and CCNG2 were dysregulated in head and neck cancer, we generated Kaplan–Meier curves and estimated the effect of CCNG1/CCNG2 expression status on survival." (PMID 27982046, 2016). "The expression level of CycG1 (CCNG1) was reduced in bladder cancer, head and neck cancer, and sarcoma relative to normal solid tissue, whereas CycG2 (CCNG2) expression was reduced in colon cancer, head and neck cancer, and rectal cancer." (PMID 27982046, 2016).
melanoma (2 papers, 2007 to 2021). A malignant, usually aggressive tumor composed of atypical, neoplastic melanocytes. "Among down-regulated genes, the analysis showed several experimentally validated target genes, such as E2F7, MAP2K1 (also known as MEK1), CCNG1, HMGB2, SIRT1, belonging to key signaling pathways frequently associated to melanoma." (PMID 33670365, 2021).
renal fibrosis (2 papers, 2022 to 2023). A final common manifestation of a wide variety of chronic kidney diseases characterized by glomerulosclerosis and tubulointerstitial fibrosis. "Knockout of cyclin G1 and inhibition of 4E-BP1 (a downstream molecule of the mTORC1 pathway) both alleviate the arrest of the G2/M phase and renal fibrosis, suggesting a connection between cell-cycle dysregulation and renal fibrosis." (PMID 36768457, 2023).
sarcoma (2 papers, 2016 to 2025). A usually aggressive malignant neoplasm of the soft tissue or bone. "Recently, CCNG1 expression was further evaluated in 179 sarcoma tumors, and the results of DNG64-treated patients with known CCNG1 expression levels were reported." (PMID 40227707, 2025).
serous ovarian cancer (2 papers, 2019 to 2024).
Alzheimer disease (1 paper, 2026). A progressive, neurodegenerative disease characterized by loss of function and death of nerve cells in several areas of the brain leading to loss of cognitive function such as memory and language. "The CCNG1 locus risk allele increased the risk of Alzheimer's disease (p<0·0001, OR 9·56 [4·29-21·24]) and reduced the age at dementia onset (p=0·0068, β=-10·15 [95% CI -17·31 to -2·77])." (PMID 42127933, 2026).
cerebral infarction (1 paper, 2023). An ischemic condition of the brain, producing a persistent focal neurological deficit in the area of distribution of the cerebral arteries. "This study aimed to explore the clinical value of miRNA-122 in patients with ACI and the related mechanism of regulating the proliferation and apoptosis of vascular endothelial cells by targeting CCNG1, to provide a new perspective for the diagnosis and treatment of cerebral infarction." (PMID 37119591, 2023).
endometriosis (1 paper, 2024). The growth of functional endometrial tissue in anatomic sites outside the uterine body. "Comparative studies involving cervical epithelium from women with and without moderate or severe endometriosis reveal elevated expression of genes associated with endometriosis, including cyclin B1 (CCNB1) and cyclin G1 (CCNG1)." (PMID 38398227, 2024).